RN7SL728P (RNA, 7SL, cytoplasmic 728, pseudogene)
Gene: Miscellaneous RNA gene on chromosome 4 (102,348,392 to 102,348,691, reverse strand). Ensembl gene ENSG00000241144.
Homologues: Orthologues: chimpanzee Metazoa_SRP (96% identical), macaque Metazoa_SRP (88% identical). Paralogues in human: RN7SL2 (78% identical), RN7SL3 (77% identical), RN7SL1 (77% identical), RN7SL127P (74% identical), RN7SL220P (74% identical), RN7SL825P (74% identical), RN7SL300P (74% identical), RN7SL444P (74% identical), RN7SL492P (74% identical), RN7SL408P (74% identical), RN7SL498P (73% identical), RN7SL660P (73% identical), and 696 more.